MMP1 (matrix metallopeptidase 1)
Diseases named in the same sentence as MMP1 in open-access papers (continued):
Sharing a sentence is not in itself a finding about the gene and the disease.
mesothelioma (4 papers, 2000 to 2024). A usually malignant and aggressive neoplasm of the mesothelium which is often associated with exposure to asbestos. "Using immunohistochemical staining, the authors observed that the tumour expressed MMP-1, an enzyme known to increase the invasiveness of mesothelioma cells." (PMID 29623449, 2018). "The mesothelioma cell lines synthesized a panel of matrix metalloproteinases critical for tumour progression such as MMP-1, 2, 3, 9 and membrane-bound MT1-MMP." (PMID 11027427, 2000). "The role of MMP-1 has previously been discussed in relation to splenic angiosarcoma, a cancer that can metastasise to the membranes of both the peritoneum and pleura, much like mesothelioma." (PMID 29623449, 2018). "In summary, we found that the transcript levels of EGFR and MMP1 were downregulated, while EPHA5 and PARK2 were upregulated in response to YB‐1 knockdown using both siRNAs in mesothelioma cells." (PMID 36550787, 2024). "We then expanded the gene panel to include ITGA6, PD-L1, and MMP1, which were previously shown to be upregulated by EGF in EMT models of mesothelioma." (PMID 33777943, 2021).
metastatic melanoma (4 papers, 2007 to 2024). A melanoma that has spread from its primary site to another anatomic site. "In addition, high expression of MMP-1 was correlated with shorter disease-free survival in metastatic melanoma." (PMID 20959825, 2010).
osteomyelitis (4 papers, 2019 to 2024). An acute or chronic inflammation of the bone and its structures due to infection with pyogenic bacteria. "We have previously found that variants in the genes of IL-1α, MMP1, TLR4 receptor, endothelial nitric oxide synthase (NOS3), Bax and tPA also contribute to the risk of developing osteomyelitis with prevalences of between 3.8% and 65.3%." (PMID 31647805, 2019). "Serum MMP-1 levels were significantly lower in osteomyelitis patients with acute infection who were carriers of the G allele of the N125S polymorphism compared to those with the AA genotype (p = 0.024)." (PMID 31647805, 2019). "CTSG N125S polymorphism was genotyped in 329 osteomyelitis patients and 415 controls), Blood coagulation parameters, serum CTSG activity, LF, MMP-1, MMP-13, and soluble receptor activator for nuclear factor κ B ligand (sRANKL) levels were assessed in carriers of the different CTSG genotypes." (PMID 31647805, 2019). "Finally, we identified CXCL10 and MMP1 as the core genes for osteomyelitis and DFU." (PMID 37904457, 2023). "The findings suggest potential linkages between SNPs in genes such as IL-1, IL-6, IFN-γ, TNF-α, VDR, tPA, CTSG, COX-2, MMP1, SLC11A1, Bax, NOS2, and NLRP3 with the development of osteomyelitis." (PMID 39301021, 2024). "We have reported increased plasma levels of MMP-1 and MMP-13 in osteomyelitis patients in a previous work." (PMID 31647805, 2019). "Current research has amassed increasing evidence suggesting that SNPs in various genes, including IL-1, IL-6, IFN-γ, TNF-α, VDR, tPA, CTSG, COX-2, MMP1, SLC11A1, Bax, NOS2, and NLRP3, may contribute to the development of osteomyelitis." (PMID 39301021, 2024). "However, although MMP-1 plasma levels were increased in osteomyelitis AA carriers, MMP-1 plasma levels were not increased but were significantly decreased in the osteomyelitis patients with the CTSG N125S allele in this study." (PMID 31647805, 2019).
osteoporosis (4 papers, 2017 to 2023). A condition of reduced bone mass, with decreased cortical thickness and a decrease in the number and size of the trabeculae of cancellous bone (but normal chemical composition), resulting in increased fracture incidence. "MLN64-knockdown alleviates the severity of osteoporosis, down-regulates specific genes related to osteoclastogenesis including Runx2 and inflammatory factors such as TNF-α, IL-1β, IL-6, and MMP-1." (PMID 36387862, 2022).
psoriasis (4 papers, 2016 to 2025). An autoimmune condition characterized by red, well-delineated plaques with silvery scales that are usually on the extensor surfaces and scalp. "As the key cytokines in the pathogenesis of psoriasis, IL-17A can synergize with TNF-α to induce the production of MCP-1, IL-8, and MMP-1 by dermal fibroblasts." (PMID 28217129, 2017). "A representative proinflammatory cytokine, IL-18, has been classified as a biomarker for the activity of psoriasis, in addition to other cytokines including transforming growth factor beta 1 (TGF-β1), tissue inhibitor of metalloproteinase 1 (TIMP-1), and matrix metalloproteinase 1 (MMP-1)." (PMID 26901187, 2016).
psoriatic arthritis (4 papers, 2021 to 2025). Joint inflammation associated with psoriasis. "The excessive and progressive cleavage of CII by members of the collagenase subfamily of MMPs such as MMP-1, -8, -13, and -14 has been observed in RA, psoriatic arthritis (PsA), and the early stages of OA." (PMID 37629227, 2023). "However, the results for MMP1 appear to be inconsistent in that the serum MMP1 levels of psoriatic arthritis patients (4.40 ± 2.37 ng/mL) were significantly lower compared to the control levels (7.27 ± 3.78 ng/mL)." (PMID 37513300, 2023). "Previous studies have demonstrated that MMP-1 secretion was higher in the RA (including early RA) groups compared with the OA or non-RA (other inflammatory arthritis like psoriatic arthritis (PsA) and AS)." (PMID 35126351, 2021).
pulpitis (4 papers, 2017 to 2024). Inflammation of the dental pulp. "Recent studies have shown that MMPs take part in pulpitis, and the levels of MMP-1 and MMP-2 are considerably higher in pathological pulp tissue than in healthy pulp tissue." (PMID 33628825, 2021). "However, the increase of MMP-1 protein induced by pulpitis or periapical periodontitis can lead to pathological processes, including ECM breakdown." (PMID 29054963, 2017). "The molecular characterization of proteins in irreversible pulpitis includes MMP-12, MMP-9, RANTES, MIP-2, MCP-1, MMP-2, MMP-1, and P-Selectin, which exhibited correlations of ≥0.8 with the duration of pain caused by cold." (PMID 38279358, 2024). "Our study has shown that the activation of proteolytic enzymes MMP-1 and MMP-2 is increased in acute experimental pulpitis induced by LPS." (PMID 33628825, 2021).
sarcoidosis (4 papers, 2019 to 2024). Sarcoidosis is a multisystemic disorder of unknown cause characterized by the formation of immune granulomas in involved organs. "In the veterinary literature, overexpression of MMP1 in association with infiltrative growth has been reported for bovine papillomavirus type 1-induced equine sarcoids, and canine oral melanoma." (PMID 31640696, 2019). "MMP1 transcription was recently shown to be upregulated in EcPV2-associated genital SCCs, and over-expression of this proteinase has been previously demonstrated to correlate with progression of bovine PV-induced equine sarcoids." (PMID 31640696, 2019). "Compared to sarcoidosis, the most upregulated gene in TB was the collagenase matrix metalloproteinase-1 (MMP-1)." (PMID 39717773, 2024). "Some groups suggested both markers as IPF-specific predictors while another group reported higher serum and bronchoalveolar lavage fluid concentrations of MMP1 in sarcoidosis compared with higher concentrations of MMP7 in IPF in each fluid." (PMID 35203313, 2022). "Additionally, MMP1 showed increased expression in sarcoidosis." (PMID 35203313, 2022). "Previous reports have demonstrated plasma MMP-1 levels to be significantly higher in patients with PTB than in healthy controls and patients with LTBI or sarcoidosis." (PMID 31917802, 2020). "However, data on MMP1 and MMP7 as potential serum biomarkers for IPF and/or sarcoidosis are controversial." (PMID 35203313, 2022).
Sciatica (4 papers, 2009 to 2018). Pain in the lower back and hip radiating in the distribution of the sciatic nerve. "Polymorphisms of MMP-1 have been associated with an increased risk of developing lumbar disc disease and may contribute to LBP, sciatica, and disability after lumbar DH." (PMID 26743937, 2016). "Genetic variability in MMP1 has also been suggested to contribute to low back pain and sciatica." (PMID 25207923, 2014). "Moreover, the anti-inflammatory agents' impact was observed in active components of both MMP-1 and MMP-3, suggesting that using these drugs could, at least under certain conditions, alter the speed and extent of DH resorption after an episode of sciatica." (PMID 19906289, 2009).
stomach cancer (4 papers, 2014 to 2022). "The functional importance of MMP-1 polymorphisms in lower stomach tumor formation was confirmed by haplotype effects of these polymorphisms on MMP-1 expression levels in serum." (PMID 24505369, 2014). "In conclusion, our study suggests that MMP-1.3, MMP-1.4 and MMP-1.5 polymorphisms in the MMP-1 promoter enhances the risk of lower stomach tumor formation in an eastern Indian population." (PMID 24505369, 2014).
thoracic aortic aneurysm (4 papers, 2009 to 2024). An aneurysm formed in the wall of the proximal portion of the descending aorta proceeding from the arch of the aorta. "The fact that higher tissue MMP-1 levels have been associated with thoracic aortic aneurysm and thoracic aortic dissection also indicates that higher MMP-1 levels may result in decreased thoracic aortic collagen content and/or concentration leading to decreased arterial stiffness." (PMID 29070037, 2017). "The aim of our study is to evaluate the levels of serum MMP-1, -2, -3 and -9 in acute and chronic aortic dissection, thoracic aortic aneurysm and acute myocardial ischemia compared to normal individuals and assess their clinical significance." (PMID 19886986, 2009).
apical periodontitis (3 papers, 2017 to 2020). "In a sample of 326 subjects, the alternative variant of MMP-1 rs1799750 was associated with increased risk to suffer from apical periodontitis." (PMID 31379856, 2019). "Additionally, the cytokines TNFα, IL-21, IL-17A, and IFN-γ were associated with augmented transcriptional activity of MMP-1 in apical periodontitis, favoring its development." (PMID 31379856, 2019).
Atherosclerotic lesion (3 papers, 2014 to 2023). A lesion associated with atherosclerosis, a multifactorial and multipart progressive disease manifested by the focal development within the arterial wall of lesions, that ranges from the development of a fatty streak, plaque progression, and plaque disruption. "Macrophage accumulation and MMP1 expression have been shown previously to be stress and strain sensitive in atherosclerotic lesions." (PMID 25365517, 2014). "Results showed that LECT2 reduced total cholesterol and low-density lipoprotein concentrations in serum and inhibited the development of atherosclerotic lesions, accompanied by reductions in inflammatory cytokines and lower MCP-1, MMP-1, TNF-α, IL-8, and IL-1β mRNA abundance." (PMID 31310065, 2019).
atrial fibrillation (3 papers, 2019 to 2022). A disorder characterized by an electrocardiographic finding of a supraventricular arrhythmia characterized by the replacement of consistent P waves by rapid oscillations or fibrillatory waves that vary in size, shape and timing and are accompanied by an irregular ventricular response. "Furthermore, the biomarker combination of high serum PICP and low serum CITP:MMP-1 ratio is associated also with increased risk of HF hospitalization and mortality, as well as with atrial fibrillation." (PMID 32028612, 2020).
Barrett's metaplasia (3 papers, 2010 to 2019). "The role of MMP1 in early disease was reported in another study that identified MMP1 as a pre-invasive factor in Barrett’s oesophagus-associated OAC." (PMID 31391080, 2019). "The expression of MMP1 was confirmed in 95% of patients with OAC and Barrett’s oesophagus, furthermore, in vitro MMP1 expression strongly correlated with proliferation." (PMID 31391080, 2019). "No data are currently available which connect expression of MMP-1 and MMP-13 with Barrett's metaplasia and related EACs with the tumor proliferation model of multistep carcinogenesis and clinicopathologic features." (PMID 20946664, 2010).
bone metastasis (3 papers, 2013 to 2022). Transfer of a neoplasm from its primary site to bones. "Case No. 14 showed bone metastasis with recovered levels of miR-21 and a normal range for MMP-1/CD63." (PMID 31537868, 2019).
brain tumors (3 papers, 2022 to 2025). "In these brain tumours, loss of WWOX expression removes repression of pro-invasive genes such as MMP1, thereby facilitating HIF1A-driven ECM remodelling, which exacerbates tumour aggressiveness and further undermines genomic stability." (PMID 41007296, 2025). "Despite general assumptions that MMP-1 should not be present in human brain tumors, mainly due to the lack of significant amounts of collagen in the brain structures, the level of MMP-1 in fact increases with an increase in the degree of malignancy of the disease and its invasiveness." (PMID 36291686, 2022). "As the genes for MMP1 and MMP13 were not amplified in the control samples, it was not possible to determine the fold change in these genes in the examined brain tumors." (PMID 38474106, 2024).
carpal tunnel syndrome (3 papers, 2013 to 2020). Entrapment of the median nerve in the wrist that is characterized by numbness, tingling and painful movement. "DNA variants located within MMP1 (rs1799750), MMP3 (rs3025058, rs679620, rs591058, rs650108), MMP10 (rs486055), and MMP12 (rs2276109), have independently and/or in combination been associated with Achilles tendinopathy (AT) risk, Carpal Tunnel Syndrome (CTS) and ACL ruptures." (PMID 32650441, 2020). "Studies have shown increased MMP-1 or MMP-2 with chronic loading of tendons in tendons with signs of overuse injury and in flexor tendosynovial tissues collected from patients with carpal tunnel syndrome." (PMID 26781840, 2016).
cerebral infarction (3 papers, 2018 to 2021). An ischemic condition of the brain, producing a persistent focal neurological deficit in the area of distribution of the cerebral arteries. "In this study, vx-765 treatment enhanced the expression levels of TIMP-1 and TIMP-2 but reduced the expression levels of MMP-1, MMP-2, MMP-3, and MMP-9 proteins after cerebral infarction." (PMID 33584203, 2020).
colon adenocarcinoma (3 papers, 2022 to 2024). "In another study, inhibition of MMP1 by chemical inhibitor or neutralizing antibodies impaired angiogenesis, primary tumor growth and lung metastasis in murine C26 colon adenocarcinoma." (PMID 35163100, 2022).
dementia (3 papers, 2013 to 2025). Loss of intellectual abilities interfering with an individual's social and occupational functions. "Addition of GDF15 and MMP1 modestly increased the C-statistic for dementia from 0.63 to 0.68." (PMID 39695064, 2025). "However, MMP-1 expression has been reported to be increased following HIV-1 infection of monocytes/macrophages with cell free virus and expression of MMP-1 at the mRNA and protein level was found increased in infected brain tissues in patients with HIV-1 associated dementia." (PMID 23383108, 2013). "The greatest risk was conferred by the highest quartiles of GDF15, TNFR1, MMP1, MMP7, and μPAR, with participants in Q4 for each biomarker having a HR ≥ 1.6 for incident dementia relative to those in Q1." (PMID 39695064, 2025).
dental caries (3 papers, 2014 to 2025). The decay of a tooth, in which it becomes softened, discolored, and/or porous. "MMPs present in saliva (MMP-1 and -8) and sound dentin (MMP-1, -2, -3, -9, and -20) are promising candidates for the degradation of demineralized dentin organic matrix, and host susceptibility to dental caries might depend on variation in MMP activity in saliva and dentin." (PMID 25083880, 2014).
dermatitis (3 papers, 2012 to 2025). An inflammatory process affecting the skin. "ASE not only markedly decreased several components of retinoid-induced dermatitis, it but also boosted the ability of retinoids to inhibit MMP-1 protein expression, suggesting that it could enhance the antiwrinkle effects of retinoids." (PMID 21912567, 2012).
diabetic macular edema (3 papers, 2016 to 2022). "Patients with diabetic macular edema are characterized by higher levels of MMP-1 and MMP-9 in the aqueous humor compared to patients without, suggesting that these two enzymes promote the prevalence of diabetic macular edema." (PMID 35457074, 2022). "In the AH of diabetic macular edema patients, MMP-1 and MMP-9 concentrations are higher than normal." (PMID 32596291, 2020). "We hypothesize that MMP-1 and MMP-9 have major roles in the initiation of inner BRB damage and in the induction of diabetic macular edema (DME)." (PMID 27467659, 2016).
diabetic nephropathy (3 papers, 2014 to 2020). "The rs35068180 located in the gene that codes for the matrix metalloprotease 3 (also known as Stromelysin 1) has been related to diabetic nephropathy, and its combination with the rs1799750 located in the MMP1 gene strongly associates to end stage renal disease." (PMID 30863424, 2019). "In studies in patients with diabetic nephropathy, the administration of vitamin E caused a reduction in the serum concentration of MMP-2, MMP-9, and TNF-α, while zinc was shown to decrease the Cd-induced expression of MMP-1 in synoviocytes." (PMID 32927885, 2020).
dysplasia (3 papers, 1998 to 2022). A usually neoplastic transformation of the cell, associated with altered architectural tissue patterns. "Positive MMP1 cytoplasmic staining was commonly observed in carcinoma (100%, 10/10), hyperplasia (60%, 6/10), and dysplasia/carcinoma in situ (60%, 6/10), but much less in samples with healthy mucosa (20%, 2/10)." (PMID 36105241, 2022).
Ewing sarcoma (3 papers, 2013 to 2022). A small round cell tumor that lacks morphologic, immunohistochemical, and electron microscopic evidence of neuroectodermal differentiation. "It is associated with the invasiveness and metastasis of Ewing sarcoma via the regulation of PGF and MMP1." (PMID 35159080, 2022). "Furthermore, G-protein coupled receptor 64 also promoted MMP-1 expression and cell motility of Ewing sarcomas." (PMID 23892595, 2013). "Previous studies have shown that GPR64 promotes the invasion and metastasis of Ewing’s sarcoma through PGF and MMP1." (PMID 34122521, 2021).
glomerulosclerosis (3 papers, 2011 to 2019). A hardening of the kidney glomerulus caused by scarring of the blood vessels. "Here, Up/cr ratio showed higher positive correlation with glomerulosclerosis, than with an index of tubular damage, and was also in accordance with the MMP-1 protein expression." (PMID 27560781, 2016).
gout (3 papers, 2023 to 2026). A condition characterized by painful swelling of the joints, which is caused by deposition of urate crystals. "Six significantly distinct proteins were identified in the serum proteomic profile of gout flares, these patients having elevated circulating concentrations of MMP-1, IL-6, VEGFA, and CCL23 and decreased DNER (Delta and Notch-like epidermal growth factor-related receptor) and CD6 levels." (PMID 37810213, 2023). "Firstly, the proteins identified as differentially expressed between gout and healthy controls, such as VEGF-A, MMP-1, TGF-α, and OSM, show high discriminative power and may serve as potential biomarkers for gout diagnosis." (PMID 39611154, 2024).